ZEB1 (zinc finger E-box binding homeobox 1)
Diseases named in the same sentence as ZEB1 in open-access papers (continued):
Sharing a sentence is not in itself a finding about the gene and the disease.
triple-negative breast carcinoma (46 papers, 2010 to 2025). An invasive breast carcinoma which is negative for expression of estrogen receptor (ER), progesterone receptor (PR), and human epidermal growth factor receptor 2 (HER2). "In contrast, we have previously shown that transient transfection of the miR-200c mimic into MDA-MB-231 (an aggressive triple negative breast cancer cell line) and Hec50 (an aggressive Type 1 endometrial cancer cell line) causes a marked repression of ZEB1 and a restoration of E-cadherin expression." (PMID 20049172, 2010). "We analyzed ChIP-seq data of ZEB1 genomic binding in mesenchymal triple-negative breast cancer (TNBC) cell line MDA-MB-231." (PMID 40940864, 2025). "For example, YTHDF3 positively regulates NSCLC cells’ migration, invasion, and EMT in triple-negative breast cancer cells through enhancing ZEB1 mRNA stability in an m6A-dependent manner." (PMID 38992016, 2024). "The correlation between ZEB1 and vimentin expression in triple-negative breast cancer and metaplastic breast carcinoma tumor cohorts further highlighted its role." (PMID 39256881, 2024). "Cellular function experiments were conducted to evaluate the role of NOTCH3/miR-223/ZEB1 in the proliferation and invasion of triple-negative breast cancer (TNBC)." (PMID 38164285, 2024). "miR-508-3p hindered the EMT by targeting ZEB1 to inhibit cell invasion in triple-negative breast cancer." (PMID 37048561, 2023). "SLFN12 overexpression accelerated ZEB1 proteasome degradation and slowed ZEB1 translation in triple-negative breast cancer cells." (PMID 35216035, 2022). "MiR-873 downregulation in triple-negative breast cancer (TNBC) promotes gemcitabine resistance through elevating the level of zinc finger E-box binding homeobox 1 (ZEB1), which interacts with YAP to activate gene transcription." (PMID 33467099, 2021). "While excess HA induced ZEB1 expression, blocking HA synthesis reduced ZEB1 levels in triple-negative breast cancer cells." (PMID 28086235, 2017). "Integrating genetic and pharmacological approaches in vitro and in vivo we demonstrate that the pro-invasive activity of LPA on triple negative breast cancer cells depends on an LPA1/PI3K/ZEB1/miR-21 activation cascade." (PMID 26098771, 2015). "Similarly, circ-ZEB1 was one of the oncogenic circRNAs that was significantly higher in triple-negative breast cancer (TNBC) tumor tissues and tumor cell lines." (PMID 35865469, 2022). "In addition, circRNA circ-ZEB1, acting as a ceRNA to modulate the expression of miR-448, facilitated the cell proliferation and invasion of triple negative breast cancer cells." (PMID 34257535, 2021). "In this study, we show that SNAI2, a mediator of EMT highly expressed in triple-negative breast cancer, is upregulated in endocrine-resistant cells, whereas other EMT-associated transcription factors, such as SNAI1/3, TWIST1/2, ZEB1/2, FOXC2, and GSC, are unaltered." (PMID 29921289, 2018). "Lut reverses EMT by inhibiting NF-κB/zinc finger E-box binding homeobox 1 (ZEB1), reducing metastasis in triple-negative breast cancer." (PMID 41479912, 2025). "CNS5 attenuates ZEB1 ubiquitination which finally leads to altered ZEB1 expression, which is key for the EMT process in triple-negative breast cancer and leads to disease progression." (PMID 35342335, 2022). "The Cancer Genome Atlas (TCGA) database analysis showed high gene significance for ZEB1 with EMT module analysis and miR-221 overexpression within the triple-negative breast cancer (TNBC) and HER2+ subgroups when compared to luminal A/B subgroups." (PMID 33327491, 2020). "FosL1/AP-1 signaling has also been reported to modulate ZEB1/2 and TGF-β expression to induce EMT in triple-negative breast cancer cells." (PMID 26754630, 2016). "A recent report demonstrated that expression of the M276I mutant MORC2 in triple-negative breast cancer cells promoted Slug protein and mRNA expression, but not Snail, Twist, and Zeb1." (PMID 31180332, 2019).
triple-negative breast carcinoma (continued). "Interestingly, the aggressive claudin-low subtype of triple-negative breast cancers showed high expression of HAS2, CD44 and ZEB1." (PMID 28086235, 2017). "In line with this notion, a recent study using CRISPR-CAS9 to knock-out ZEB1, a homeobox transcription factor that mediates epithelial to mesenchymal transition (EMT) in response to TGF-ß, found that Teneurin-2 transcription is directly repressed by ZEB1 in triple-negative breast cancer cells." (PMID 30618566, 2018).
non-small cell lung carcinoma (45 papers, 2013 to 2025). A group of at least three distinct histological types of lung cancer, including non-small cell squamous cell carcinoma, adenocarcinoma, and large cell carcinoma. "There is a strong association between FBXO11 and ZEB1 in non-small cell lung cancer (NSLC) in a clinical database." (PMID 39409891, 2024). "For example, EMT-TFs such as TWIST1 and ZEB1 have been reported to drive EMT-mediated resistance to EGFR inhibitors in EGFR-mutant non-small cell lung cancer." (PMID 36781842, 2023). "Nrf2 has been deciphered as another important PSF for hybrid E/M forms whose constitutive expression upregulated both E-cadherin and ZEB1 in non-small cell lung carcinoma (NSCLC) and bladder cancer cells." (PMID 36467417, 2022). "Another interesting study discloses that AKIP1 activates Zinc Finger E-Box Binding Homeobox 1 (ZEB1) to facilitate tumor metastasis in non-small cell lung cancer." (PMID 35965570, 2022). "Silencing SNHG3 is a controller of the miR-216a/ZEB1 axis in non-small cell lung cancer (NSCLC) to constrain cancer malignant progression." (PMID 35123415, 2022). "MiR-455 inhibited the proliferation, migration, and invasion of non-small cell lung cancer cell lines by targeting ZEB1." (PMID 34539879, 2021). "Loss of E-cad stimulates EGFR-MEK/ERK signaling, which promotes invasion via the ZEB1/MMP2 axis in non-small cell lung cancer." (PMID 31952541, 2020). "Long non-coding RNA linc00673 regulated non-small cell lung cancer proliferation, migration, invasion and epithelial mesenchymal transition by inhibiting miR-150-5p and modulate ZEB1 expression." (PMID 30098599, 2018). "In non-small cell lung cancer (NSCLC) cell lines, we and others previously found that loss of E-cadherin was inversely and specifically correlated with ZEB1 mRNA expression." (PMID 24216980, 2013). "Reciprocal expression of ZEB1 and E-cadherin has also been observed in non-small cell lung carcinoma." (PMID 23844063, 2013). "We first verified decreased mRNA levels of the ZEB1-negatively correlated genes after ZEB1 induction in H358 non-small cell lung cancer cells." (PMID 24216980, 2013). "In addition, the MIAT/miR-150-5p/ZEB1 signaling pathway plays an oncogenic role in non-small cell lung cancer." (PMID 34811354, 2021). "In non-small cell lung cancer, lncRNA linc00673 could regulate the expression of ZEB1, a key regulator in EMT." (PMID 33193573, 2020). "Additionally, in non-small cell lung cancer, ZEB1, as a target of miR-445, reverses its inhibition of the proliferation, migration and invasion." (PMID 31007650, 2019). "Furthermore, a recent study has implied that miR-5702 suppresses proliferation and invasion in non-small-cell lung cancer cells via posttranscriptional suppression of ZEB1." (PMID 31399501, 2019). "Activation of ALK/STAT3 in T cell lymphoma, AP-1/JAK/STAT in classical Hodgkin lymphoma (cHL), the microRNA-200/ZEB1 axis in non-small-cell lung cancer (NSCLC), c-jun/STAT3 in BRAF inhibitor-resistant melanoma, and PI3K in glioma have each been reported to upregulate PD-L1 expression on tumor cells." (PMID 31730010, 2019). "Latest study confirmed the interaction of miR-409-3p and ZEB1 played a role in the progression process of non-small cell lung cancer, indicating ZEB1 acted as a direct target of miR409-3p and could be modulated by miR-409-3p." (PMID 30846940, 2019). "LncRNA-HIT promotes metastasis in NSCLC (non-small cell lung cancer) via specially binding to ZEB1." (PMID 29416704, 2018). "Upregulation of miR-199a-3p inhibits the expression of zinc‐finger E‐box-binding homeobox 1 (ZEB1) to restrain the tumor stem-like properties in non-small cell lung carcinoma (NSCLC) cells." (PMID 34632938, 2021).
non-small cell lung carcinoma (continued). "Nuclear factor erythroid 2-related factor 2 (Nrf2) has been deciphered as another important PSF for hybrid E/M form, whose constitutive expression upregulated both E-cad and ZEB1 in non-small cell lung carcinoma (NSCLC) and bladder cancer cells." (PMID 33207810, 2020). "However, the roles of circ-ZEB1 in non-small cell lung cancer (NSCLC) are unknown." (PMID 39802932, 2025). "In non-small cell lung cancer (NSCLC) cells, ZEB1-mediated suppression of E-cadherin can induce migration, invasion, and activation of the epidermal growth factor receptor (EGFR)." (PMID 35454770, 2022). "For instance, in non-small cell lung cancer cells, downregulation of Rhomboid domain containing 1 (RHBDD1) expressions inhibits cell growth and invasion through reducing the ZEB1/PI3K/AKT signaling pathway activation." (PMID 34539879, 2021). "NCI-H358 non-small cell lung cancer (NSCLC) cells engineered to express Snail, Zeb1 or activated TGF-β exhibited aTGFβ expression and phenotypic changes consistent with EMT and a shift to a more invasive phenotype." (PMID 33478130, 2021). "LINC00673 sponges miR-150-5p to modulate the expression of zinc finger E-box binding homeobox 1 (ZEB1), a key epithelial–mesenchymal transition regulator, in non-small cell lung cancer." (PMID 32429086, 2020). "In this study, expression levels of miR-200c and miR-9, ZEB-1, ZEB-2 and E-cadherin were assessed in 30 non-small cell lung cancers (NSCLCs) by real-time qPCR." (PMID 31244281, 2019). "Within non-small cell lung cancer (NSCLC) cells it was found that with the suppression of E-Cadherin, ZEB1 has the ability to increase invasion via transcriptional activation of MMP-2 as well as cause aberrant EGFR signaling." (PMID 32309604, 2018). "In non-small-cell lung cancer cell line, knockdown of MIAT resulted in decreased ZEB1 expression, indicating cis-action of MIAT on regulating ZEB1." (PMID 30119681, 2018). "As the previous study showed that miR-455 exerted anti-cancer effects in non-small cell lung cancer through targeting the EMT inducible transcription factor ZEB1 16, we aimed to investigate if the miR-455/ZEB1 axis was also involved in EMT in CCA in this study." (PMID 34539879, 2021). "Interestingly, Liu and colleagues reported that E6 and E7 oncoproteins enhance the expression of HIF-1α, as well as of ZEB-1, SNAIL-1, SLUG, and TWIST-1 in non-small cell lung cancer (NSCLC) cells, thus promoting the EMT process." (PMID 33297475, 2020). "The trimodal distribution of ZEB1 from the TCS modeling analysis is further supported by gene expression data from NCI-60 cell lines and the immunofluorescence (IF) results of the hybrid E/M non-small cell lung cancer (NSCLC) cell line – H1975." (PMID 29623961, 2017). "Recent work has shown that, in non-small cell lung cancer (NSCLC), elevated levels of iATP via macropinocytosis-mediated eATP internalization subsequently upregulates mesenchymal markers such as vimentin and EMT master transcription factors including SNAIL and ZEB1." (PMID 36750864, 2023). "In non-small cell lung carcinoma cells with overt signs of EMT and resistance to radiation therapy, weak signaling by LKB1 and SIK kinases could be measured, resulting in derepression of the EMT transcription factor ZEB1." (PMID 29464029, 2018).
breast tumor (42 papers, 2008 to 2025). "ZEB1 expression is a hallmark of claudin-low breast tumors and ZEB1 counteracts the onset of oxidative stress in response to oncogene-induced replicative insults." (PMID 34458275, 2021). "Herein we showed by analyzing publicly available expression data from 1488 human primary breast tumors that the gene encoding the transcription factor ZEB1 was the most correlated with LPAR1 encoding LPA1." (PMID 26098771, 2015). "ZEB1 mRNA levels are inversely associated with high-grade breast tumors and appear to be involved in tumor metastasis and poor patient survival." (PMID 25749031, 2015). "Epigenetic shifts induced by ZEB1‐silencing are enriched in a subset of human breast tumors, illuminating a clinically‐relevant hybrid‐like state." (PMID 37217832, 2023). "In breast tumors, for example, high expression of the ZEB1/YAP1 target genes results in a significantly shorter relapse-free and overall survival." (PMID 36936987, 2023). "Our model suggests that targeted epigenetic silencing of ZEB1 is sufficient to induce an epigenetic landscape that resembles the hybrid‐like states present in human breast tumors." (PMID 37217832, 2023). "ZEB1 regulates upregulated genes in breast tumor tissue; however, this transcription factor was found to be downregulated in the present study." (PMID 36982287, 2023). "Such a shift towards CD44s induced by EMT transcription factors Snail or ZEB1 in breast tumor cell backgrounds has previously been reported by others." (PMID 35805061, 2022). "The coexpression of ZEB1 and ERα in breast tumor cells in situ confirms our findings with tissue culture cells regarding the possibility to form a ZEB1-ERα TF complex in cells with partial EMT states." (PMID 35440541, 2022). "In CAF-admixed breast tumor xenografts, we observed the induction of the E/M state as evidenced by ZEB1 expression in tumor cells adjacent to CAFs at the tumor–stroma interface." (PMID 31331982, 2019). "Consistently, The Cancer Genome Atlas RNASeq data set on human primary breast tumors (n=970) indicated that high levels of ZEB1 mRNA statistically correlate with high levels of EPB41L5 mRNA." (PMID 27617643, 2016). "Accumulating evidences indicate that miR-205-5p is significantly downregulated in breast tumors compared with normal breast tissue and acts as a tumor suppressor directly targeting oncogenes such as Zeb1 and ErbB3." (PMID 26181203, 2015). "As LPA mediated up regulation of both ZEB1 and miR-21 through a common LPA1/PI3K axis, and because the strong correlation between ZEB1 and LPAR1, we examined the correlation between LPAR1, ZEB1 and miR-21 in human primary breast tumors." (PMID 26098771, 2015). "Another possible explanation comes from a recent study implicating SHP2 in maintaining a pool of breast tumor-initiating cells via a c-Myc/ZEB1-dependent gene expression signature." (PMID 25026279, 2014). "Our model suggests that ZEB1 silencing by dCas9 systems reprogram the epigenetic landscape of TNBCs toward a more epithelial phenotype that most resembles the hybrid‐like states present in human breast tumors." (PMID 37217832, 2023). "We demonstrate with xenograft experiments in mice and ex vivo invasion assays that ZEB1 enhances the invasive and metastatic capacity of ERα+ breast tumor cells and that it may modify the organ tropism of disseminating cells towards bone tissue." (PMID 35440541, 2022). "Like ZEB1, BMPR2 was strongly negatively correlated with both Th1 cells and M1 macrophages, supporting an association with reduced pro-inflammatory cells within breast tumors." (PMID 31780722, 2019). "Thus, our findings suggest ZEB1-mediated silencing of Ngn3 is required for breast tumor initiation and maintenance." (PMID 28903350, 2017).
breast tumor (continued). "Therefore, ZEB1 is likely to have a key role in induction of the EPB41L5 gene in significant populations of primary breast tumors." (PMID 27617643, 2016). "Upregulation of ZEB1 has been observed in triple-negative and basal-like breast tumors." (PMID 24586203, 2014). "This is in line with the proposed hierarchy of the expression of such transcriptional factors in EMT leading to that zeb1 and twist, which apparently maintain the migratory phenotype of tumor cells, are mostly detected in the stromal compartment in breast tumor tissue." (PMID 21324165, 2011). "Similarly, senescent TINs-derived exosomes could also promote the EMT and activate FTO/ZEB1 signaling in breast tumor cells." (PMID 36302751, 2022). "This led us to ask whether ZEB1 modifies the organ tropism of ERα+ breast tumor metastases." (PMID 35440541, 2022). "The METABRIC database (1904 human breast tumors) consistently revealed a positive association of NME4 with epithelial markers CDH1 and KRT18 and a negative association with mesenchymal markers CDH2 and VIM as well as many EMT drivers like ZEB1, ZEB2, SNAI2, TWIST1, and TWIST2." (PMID 34674701, 2021). "Moreover, breast tumors that highly express ZEB1 exhibit ER-α promoter hypermethylation." (PMID 28383555, 2017). "According to a previous study, ZEB1 and ZEB2 repress E-cadherin expression, whereas ZEB2 directly interacts with the vimentin promoter in human epithelial breast tumor cells." (PMID 41002590, 2025). "To validate the relationship among β4, ZEB1, and LAMC2 in human tumors, we compared their mRNA levels in breast tumors (n = 1980) using data available from the METABRIC consortium." (PMID 38508310, 2024). "AKR1B10 induces PI3K/Akt signaling, stimulates the NF‐κB pathway, promotes the expression levels of ZEB1, Slug, and Twist in EMT induction, and increases the migration rate of breast tumor cells." (PMID 37688511, 2023). "In breast tumors the expression of Cx46 (atypical connexin for breast tissue) increased the expression of EMT markers, namely, N-cadherin, vimentin, Snail and Zeb1, and stemness markers." (PMID 36829482, 2023). "Recent studies have defined PTBP3 as a regulator of EMT that acts by governing expression of ZEB1, which establish an oncogenic function of PTBP3 in breast tumor cells." (PMID 37633911, 2023). "Our previous work also demonstrated that well-known EMT transcription factors, ZEB1 or Snail, contribute to regulate TF expression in the various EMT human breast tumor cells used in the present study." (PMID 35805061, 2022). "For example, PTBP3 can regulate the expression of the transcription factor ZEB1 by binding to the 3'UTR of its mRNA, thereby preventing its degradation, inducing the epithelial-mesenchymal transition of breast tumor cells and promoting their invasive growth and metastasis." (PMID 34234866, 2021). "Essentially, ZEB1 and POLQ expression are mutually exclusive in breast tumors." (PMID 34458275, 2021). "Interestingly and during epithelial-to-mesenchymal transition in breast tumors, LRP1 expression was derepressed through ZEB-1-dependent inhibition of LRP1-targeting miRNAs, thereby contributing to vascular mimicry of breast tumor cells." (PMID 32850302, 2020). "ZEB1 has also been shown experimentally to regulate PD-L1 expression in breast tumors, although our analysis did not identify a significant correlation between ZEB1 and PD-L1 expression." (PMID 31780722, 2019). "We found that the correlation between LPAR1 and ZEB1 was stronger in the basal subtype (R Spearma n = 0.59) of human primary breast tumors than the non-basal subtype (R Spearma n = 0.40)." (PMID 26098771, 2015). "We examined the ZEB1/MYB relation more broadly in EMT and in human breast tumors." (PMID 24283570, 2013). "However, the clinical relevance of the ZEB1-ERα target genes in different subtypes of invasive and non-metastatic breast tumors for growth, the formation of distant metastasis, and therapeutic resistance needs to be further investigated." (PMID 35440541, 2022).